IL1RL2 (interleukin 1 receptor like 2)
Description:
Receptor for interleukin-36 (IL36A, IL36B and IL36G). After binding to interleukin-36 associates with the coreceptor IL1RAP to form the interleukin-36 receptor complex which mediates interleukin-36-dependent activation of NF-kappa-B, MAPK and other pathways (By similarity). The IL-36 signaling system is thought to be present in epithelial barriers and to take part in local inflammatory response; it is similar to the IL-1 system. Seems to be involved in skin inflammatory response by induction of the IL-23/IL-17/IL-22 pathway.
Synonyms: IL-36R; IL-1Rrp2; IL1R-rp2; IL1RRP2
Tractability: Small molecule: a structure with a bound ligand is known. Antibody: an approved drug acts on it; its Gene Ontology location is reachable by antibodies, with high confidence; UniProt predicts a signal peptide or a membrane-spanning region.
Gene: Protein-coding gene on chromosome 2 (102,186,980 to 102,240,002, forward strand). Ensembl gene ENSG00000115598.
Subcellular location: Membrane
Pathways (Reactome):
Immune System: Interleukin-36 pathway; Interleukin-38 signaling
Gene Ontology:
Molecular function: interleukin-1 receptor activity; interleukin-1, type I, activating receptor activity; NAD+ nucleosidase activity, cyclic ADP-ribose generating; signaling receptor activity
Biological process: cell surface receptor signaling pathway; cellular defense response; negative regulation of inflammatory response; positive regulation of cytokine production involved in inflammatory response; regulation of inflammatory response; signal transduction; cytokine-mediated signaling pathway; defense response; interleukin-1-mediated signaling pathway
Cellular component: receptor complex; cell surface; decoy receptor complex; plasma membrane; membrane
Genetic constraint (gnomAD): Loss-of-function variants: 55 observed, 55.24 expected, observed/expected ratio (o/e) 1, 90% interval 0.8 to 1.25. The upper end of that interval is the gene's LOEUF score, 1.25, which puts it in group 5 of 6, group 1 being the genes least tolerant of losing a copy. Missense variants: 681 observed, 684.8 expected, observed/expected ratio (o/e) 0.99, 90% interval 0.93 to 1.06. Synonymous variants: 285 observed, 260.83 expected, observed/expected ratio (o/e) 1.09, 90% interval 0.99 to 1.21.
Homologues: Orthologues: chimpanzee IL1RL2 (96% identical), macaque IL1RL2 (92% identical), dog IL1RL2 (72% identical), pig IL1RL2 (67% identical), rabbit IL1RL2 (65% identical), rat Il1rl2 (65% identical), mouse Il1rl2 (65% identical), guinea pig IL1RL2 (60% identical), tropical clawed frog il1r1 (34% identical). Paralogues in human: IL1R1 (40% identical), IL1RL1 (25% identical), IL1RAPL1 (25% identical), IL1RAPL2 (24% identical), IL18RAP (23% identical), IL18R1 (23% identical), IL1RAP (21% identical), IL1R2 (15% identical), SIGIRR (13% identical), LAG3 (12% identical).
Diseases named in the same sentence as IL1RL2 in open-access papers:
IL1RL2 is named in the same sentence as 96 diseases in open-access papers, as found by Europe PMC text mining. Sharing a sentence is not in itself a finding about the gene and the disease. The quoted sentences say what the papers report.
psoriasis (49 papers, 2014 to 2025). An autoimmune condition characterized by red, well-delineated plaques with silvery scales that are usually on the extensor surfaces and scalp. "Accumulating data indicates that IL1RL2 is involved in inflammatory diseases such as psoriasis, inflammatory bowel disease, and rheumatoid arthritis." (PMID 32831121, 2020).
asthma (8 papers, 2020 to 2025). "Moreover, a whole-genome sequencing association study of asthma severity in Europeans evidenced eight genome-wide significant loci previously reported as associated with asthma (IL1RL2, TSLP, HLA-DQA1, BACH2, C11orf30, RAD51B, and GSDMB) and lung function (THSD4)." (PMID 37761964, 2023). "Using GeneAtlas data, our analysis finds 5 proteins—all interleukin receptors—whose levels causally contribute to asthma disease risk: IL1RL1, IL1RL2, IL2RA, IL4R, and IL6R." (PMID 32628676, 2020). "Given the association between eosinophils and asthma, it is worth noting that IL1RL1, IL1RL2, IL2RA, and IL4R are all linked to ‘Eosinophil count’ and ‘Eosinophil percentage’ in GeneAtlas." (PMID 32628676, 2020). "In addition, ERBB3, IL1R1, IL1RL2, IL6R, LRRC32, STAT6, and TNFRSF6B have been strongly linked to allergic diseases, such as asthma and rhinitis." (PMID 38773393, 2024). "Studies have shown a lower expression of IL1RL2 in asthma causing increased IL-1 activity due to the lack of adequate anti-inflammatory regulation." (PMID 37679381, 2023). "Prior links between these proteins and asthma or atopy exist (IL1RL1 and IL1RL2, IL2RA, IL4R, and IL6R), albeit not necessarily strong evidence for a causal link." (PMID 32628676, 2020).
colon cancer (8 papers, 2022 to 2025). "IL1RL2 (also known as Interleukin 36 receptor, IL36R) is involved in tissue fibrosis and metastatic potential in breast and colon cancers." (PMID 36746917, 2023). "Interleukin 1 Receptor-Like 2 (IL1RL2) is a receptor for IL36, and this signaling axis plays a pro-tumorigenic role in colon cancer, contributing to poor survival." (PMID 38335839, 2024).
Obesity (4 papers, 2019 to 2025). Accumulation of substantial excess body fat. "In an effort to explore mechanistically how the IL-36 family might regulate obesity and metabolic disease, we investigated what role, if any, these cytokines might play in disease pathogenesis in mice with a deficiency in the IL-36 receptor antagonist (Il36rn−/−) and the IL-36 receptor (Il1rl2−/−)." (PMID 31488830, 2019).
allergic disease (3 papers, 2023 to 2024). An immune response that occurs following re-exposure to an innocuous antigen, and that requires the presence of existing antibodies against that antigen. "Specifically, elevated levels of TNFAIP3, ERBB3, TLR1, and IL1RL2 proteins were associated with a reduced risk of allergic diseases, yielding corresponding odds ratios of 0.82 (0.76–0.88), 0.74 (0.66–0.82), 0.49 (0.45–0.55), and 0.81 (0.75–0.87), respectively." (PMID 38573314, 2024). "Among these, the increased levels of TNFAIP3, ERBB3, TLR1, and IL1RL2 proteins were associated with a reduced risk of allergic diseases, with corresponding odds ratios of 0.82 (0.76–0.88), 0.74 (0.66–0.82), 0.49 (0.45–0.55), and 0.81 (0.75–0.87), respectively." (PMID 38573314, 2024). "Nonetheless, allergic diseases exert a causal effect on the protein level of IL1RL2, suggesting that IL1RL2 could serve as a potential biomarker for allergic diseases." (PMID 38573314, 2024). "The results demonstrated a significant association of TNFAIP3, IL1RL2, IL1R1, IL6R, KYNU, and ITPKA with allergic diseases in both cohorts, further supporting the reliability of the potential drug targets identified in this study." (PMID 38573314, 2024). "IL1RL2 was identified as a potential biomarker for allergic diseases." (PMID 38573314, 2024).
autoimmune disease (3 papers, 2018 to 2024). A disorder resulting from loss of function or tissue destruction of an organ or multiple organs, arising from humoral or cellular immune responses of the individual to their own tissue constituents. "IL1RL2, IL6R, ERBB3, ICAM1, IL1R1, and GALK1 were also enriched in categories like immune system disease, autoimmune disease, skin disease, and disease of anatomical entity." (PMID 38773393, 2024).
breast carcinoma (3 papers, 2020 to 2023). "IL1RL2 plays a crucial role in the inflammatory response; it is also related to the distant metastasis of breast cancer and the tumor microenvironment." (PMID 33330631, 2020). "IL1RL2 is associated with the TEM and metastasis in breast cancer." (PMID 36890467, 2023).
plaque psoriasis (3 papers, 2023 to 2025). "IL-36 receptor expression (encoded by IL1RL2), as well as the expression of IL36A, IL36B, and IL36G are significantly upregulated in psoriasis vulgaris skin lesions, compared to healthy and non-lesional skin samples." (PMID 38162658, 2023).
acute kidney injury (2 papers, 2021 to 2023). Sudden and sustained deterioration of the kidney function characterized by decreased glomerular filtration rate, increased serum creatinine or oliguria. "Interestingly, genetically manipulated animal models lacking IL1RL2 are protected against the IL-36 triggered an inflammatory response in psoriasis and acute kidney injury models." (PMID 33589722, 2021).
bronchiolitis (1 paper, 2023). Inflammation of the bronchioles characterized by swelling of the bronchioles and mucus accumulation. "The current study has identified that cg01680062 on RUNX1 and cg08552853 near IL1RL2 are significantly associated with bronchiolitis severity." (PMID 37679381, 2023).
colorectal adenocarcinoma (1 paper, 2024). The most common type of colorectal carcinoma. "This differs from the reported expression of IL-1RL2 in epithelial cells in the human colon and IL-1RL2 ligand engagement in human cell lines with epithelial morphology and derived from colorectal adenocarcinomas." (PMID 38727323, 2024).
COVID-19 (1 paper, 2022). A disease caused by infection with severe acute respiratory syndrome coronavirus 2. "Six proteins showed sex differences in levels over time, of which 3 were also associated with severe COVID-19: CCL26, IL1RL2, and IL3RA, providing insights to better understand the marked differences in outcomes by sex." (PMID 36171541, 2022). "However, our observations on TLR5, CXCL17, CCL26, IL1RL2, and IL3RA provide clear proteins to explore to explain sex differences in COVID-19 outcomes." (PMID 36171541, 2022).
small vessel stroke (1 paper, 2024). "ABO Univariate MR of multiple cohorts revealed that the risk of small vessel stroke (SVS) increases with elevated levels of TNF‐related apoptosis‐inducing ligand (TRAIL, OR, 1.23, 95% CI, 1.08–1.39) and interleukin‐1 receptor‐like 2, (IL‐1RL2, OR, 1.29, 95% CI, 1.04–1.61)." (PMID 38340139, 2024).
tumor (18 papers, 2019 to 2025). "We observed higher expression levels of Il1rl2, Rbck1, and Ppargc1a in tumor tissues of the CRC group and higher expression levels of Adipoq and Ucn in the colon of the control group." (PMID 36591255, 2022). "IDO1, NOX1, CXCL3, IL1RL2 and NOS2 were upregulated, as their expression levels were lower in the healthy group and higher in the tumor group." (PMID 36911403, 2023). "Whether these discordant outcomes reflect differences between humans and mice, tumor-dependent expression, or, perhaps, issues with the antibodies directed against human IL-1RL2, for which true controls are lacking, remains to be determined." (PMID 38727323, 2024).
infection (9 papers, 2013 to 2023). The state of being infected such as from the introduction of a foreign agent such as serum, vaccine, antigenic substance or organism. "It is also possible that increased systemic expression of IL-33 and IL1RL2 could be attributed to the patient’s adaptive immune responses to minimize infection associated with the infiltration of bacteria into the periprosthetic tissue from the percutaneous stoma." (PMID 35617338, 2022). "Our study is the first to report on difference in TLR5, CXCL17, CCL26, IL1RL2, or IL3RA levels in sexes during infection." (PMID 36171541, 2022).
cancer (8 papers, 2019 to 2025). A tumor composed of atypical neoplastic, often pleomorphic cells that invade other tissues. "Knowledge of such functions would provide a solid foundation for the application of IL-1RL2 neutralizing antibodies and IL-36 as immune adjuvants for, for example, cancer therapy." (PMID 38727323, 2024). "Similar IL-1RL2-neutralizing antibodies are being developed; however, clinical trials are also ongoing in which IL-36 is used as an adjuvant in cancer immunotherapy (ClinicalTrials.gov ID NCT03739931)." (PMID 38727323, 2024). "Furthermore, how IL-1RL2 expressing cells control normal immune mechanisms and cancers remains ill defined." (PMID 38727323, 2024).
immune diseases (3 papers, 2023 to 2024). "The PheWAS revealed associations of IL1RL2 with immune diseases which were not supported by the colocalisation results." (PMID 38565889, 2024).
cardiovascular disease (1 paper, 2020). "No previous studies have reported on IL1RL2 in HFpEF or other cardiovascular disease." (PMID 32831121, 2020).
IL1RL2 also shares sentences with these, for which no sentence is quoted: generalized pustular psoriasis (32 papers); colitis (16); pustular psoriasis (15); Arthritis (11); dermatitis (8); inflammatory bowel disease (6); rheumatoid arthritis (5); colorectal cancer (3); palmoplantar pustulosis (3); pyoderma gangrenosum (3); atopic dermatitis (2); Crohn disease (2); diabetes (2); inflammation (2); intestinal disease (2); metabolic disease (2); Psoriasiform dermatitis (2); psoriatic arthritis (2); Sepsis (2); tuberculosis (2); abdominal aortic aneurysm (1); acne (1); allergic rhinitis (1); aspergillosis (1); atherosclerosis (1); autism (1); bacterial infection (1); bacterial vaginosis (1); Chronic colitis (1); chronic lung disease (1).
A further 48 diseases each share a sentence with IL1RL2 in 1 paper.